CTAGE8 (CTAGE family member 8)
Tractability: Antibody: UniProt predicts a signal peptide or a membrane-spanning region.
Gene: Protein-coding gene on chromosome 7 (144,266,674 to 144,269,288, reverse strand). Ensembl gene ENSG00000289604.
Subcellular location: Membrane
Gene Ontology:
Biological process: endoplasmic reticulum to Golgi vesicle-mediated transport; protein secretion; vesicle cargo loading
Cellular component: endoplasmic reticulum exit site; endoplasmic reticulum membrane; membrane
Genetic constraint (gnomAD): Missense variants: 5 observed, 49.24 expected, observed/expected ratio (o/e) 0.1, 90% interval 0.052 to 0.21. Synonymous variants: 3 observed, 16.1 expected, observed/expected ratio (o/e) 0.19, 90% interval 0.084 to 0.48.
Homologues: Orthologues: dog MIA2 (77% identical), mouse Mia2 (69% identical), rat Mia2 (68% identical), Drosophila melanogaster Tango1 (21% identical). Paralogues in human: CTAGE4 (99% identical), CTAGE9 (99% identical), CTAGE15 (97% identical), CTAGE6 (97% identical), MIA2 (83% identical), CTAGE1 (75% identical), MIA3 (27% identical), SPZ1 (8% identical), MIA (2% identical), OTOR (1% identical).